IL17RC (interleukin 17 receptor C)
Diseases named in the same sentence as IL17RC in open-access papers (continued):
Sharing a sentence is not in itself a finding about the gene and the disease.
bladder cancer (3 papers, 2016 to 2024). "Similar to IL-17 F, IL-17RC immunoreactivity located principally in mononuclear cells, transitional epithelial cells, vascular endothelial cells and some malignant cells in bladder cancer." (PMID 27716046, 2016). "We compared expression and location of IL-17 cytokine family IL-17A, IL-17E and IL-17 F and their receptors IL-17RA, IL-17RB and IL-17RC in tissues derived from subjects with cystitis, bladder polyp and bladder cancer in parallel." (PMID 27716046, 2016). "For example, elevated expressions of IL-17A, IL-17 F and IL-17RC and increased numbers of macrophages were observed in bladder cancer." (PMID 27716046, 2016). "The results of a complex study on the immunoreactivity of the ligands and receptors of the IL-17 family in patients with bladder cancer showed significantly elevated IL-17A, IL-17F, and IL-17RC immunoreactivity in the bladder cancer group but decreased IL-17E, IL-17RA, and IL-17RB immunoreactivity." (PMID 37371647, 2023). "Compared with subjects with cystitis, immunoreactivity for IL-17A, IL-17 F and IL-17RC was significantly elevated in the group of bladder cancer (p < 0.01), while immunoreactivity of IL-17E, IL-17RA and IL-17RB, and the infiltrating neutrophils were decreased (p < 0.05)." (PMID 27716046, 2016). "In the present study, expression of IL-17A and IL-17 F increased but IL-17RA decreased in bladder cancer, suggesting that IL-17A and IL-17 F are possibly expressed by different profiles of cellular populations and mainly through binding IL-17RC to exert biological effects." (PMID 27716046, 2016). "One possible explanation may be that IL-17A and IL-17 F and IL-17RC can be expressed by these macrophages in bladder cancer." (PMID 27716046, 2016). "Additionally, other changed abnormal structural cells such as endothelial cells and fibroblasts were also observed in bladder cancer, which might contribute to the increases of immunoreactivity for IL-17A, IL-17 F and IL-17RC." (PMID 27716046, 2016). "The purpose of this study was to assess the expression of CXCR2, IL-17RA, and IL-17RC genes at the mRNA level as well as tissue and serum levels of IL-17A, vascular endothelial growth factor (VEGF), and transforming growth factor β (TGF-β) in patients with bladder cancer (BC) compared to control." (PMID 38515019, 2024).
candidiasis (3 papers, 2015 to 2025). Infection with the organism Candida. "Candidiasis often occurs in individuals with an inherited (gene mutations RORγ, RORγt, STAT3, TRAF3IP2, IL-17F, IL-17RA, IL-17RC) or acquired (drug-induced) dysregulation of IL-17." (PMID 40863217, 2025). "The cytokine IL-17 (IL-17A) and its receptor subunits, IL-17RA and IL-17RC, are required for protection to most forms of candidiasis." (PMID 25849644, 2015). "Congenital immunodeficiencies with candidiasis, T lymphocyte dysfunction, and IL-17 deficiency have been described in the context of pathogenic variants in genes such as STAT3, CARD9, DOCK8, ACT1, IL-17RC, IL-17RA, and IL-17F—where fluconazole is the first-line treatment." (PMID 40686918, 2025).
lung carcinoma (3 papers, 2022 to 2023). "Several clinical studies have demonstrated an essential role of both IL-17RA and IL-17RC in cancer progression, including prostatic and lung cancer and GC." (PMID 36125689, 2023). "Herein, we observed that expressions of IL-17A and its receptor, IL-17 receptor C (IL-17RC), were elevated in LUAD tissues and were correlated with poor survival in different lung cancer cohorts." (PMID 37444399, 2023).
Acute Lymphoblastic Leukaemia (2 papers, 2023 to 2025). "Combinations of genotyped SNPs in IL‐17RC (rs708567 and rs76999397) that show significant differences between acute lymphoblastic leukaemia (ALL) patients and controls, as determined by haplotype analysis." (PMID 40887867, 2025).
allergic asthma (2 papers, 2021 to 2022). A asthma with a basis in a pathological type I hypersensitivity reaction. "Although the crucial roles of IL-17 and IL-17F in allergic airway inflammation have been extensively explored, reports on the potential role of their receptor IL-17RC subunit in allergic asthma is limited." (PMID 34180764, 2021). "In the present study, we self-assembled chitosan (CS) nanoparticles for intranasal delivery of recombinant protein IL-17RC (rIL-17RC) and preliminarily investigated its effect on a murine model of allergic asthma induced by ovalbumin (OVA)." (PMID 34180764, 2021). "To date, research on delivery of soluble IL-17RC protein through CS nanoparticles and their impact on allergic asthma has not been reported." (PMID 34180764, 2021).
breast carcinoma (2 papers, 2015 to 2023). "Here, we investigated the action of IL-17A and IL-17E on breast cancer cell lines and cell signaling events induced after recruitment of IL-17RA/IL-17RC or IL-17RA/IL-17RB receptors." (PMID 26154409, 2015). "To address this question, we assessed the expression of IL-17E, IL-17RA, IL-17RC and IL-17RB in various human breast cancer cell lines as well as in non-transformed mammary epithelial cells MCF10A, in primary tumor cells (IJG-1731) derived ex vivo from an ER-negative breast cancer biopsy." (PMID 26154409, 2015).
COVID-19 (2 papers, 2022 to 2024). A disease caused by infection with severe acute respiratory syndrome coronavirus 2. "The results also suggest that either targeting IL-17F or abrogating the activity of both cytokines, targeting their common downstream receptor IL-17RC, could be another therapeutic avenue to attenuate the severe outcomes of COVID-19." (PMID 39493750, 2024). "IL7, IL17RC, and IFNLR1 were upregulated in the early stages of COVID-19 while absent in later disease stages." (PMID 35983322, 2022).
glomerulonephritis (2 papers, 2020 to 2023). A renal disorder characterized by damage in the glomeruli. "By using Fcgr2b-/- mice that were also deficient in Act1, a crucial adaptor molecule downstream from the IL-17RA/IL-17RC complex, it was shown that IL-17A deletion significantly reduced inflammatory monocyte and neutrophil infiltration and thus the severity of glomerulonephritis." (PMID 32059488, 2020). "On the other hand, total IL-17RC knockout did not affect the course of experimental sickle-shaped glomerulonephritis, and knockdown Il17rc led to a milder form of autoimmune encephalomyelitis, which contradicts the hypothesis of increased inflammation with a decrease in IL-17RC levels." (PMID 38067176, 2023).
Insulin resistance (2 papers, 2014 to 2022). Increased resistance towards insulin, that is, diminished effectiveness of insulin in reducing blood glucose levels. "In vitro overstimulation of interleukin 17 receptor C (IL17RC), of which a high level is detected on the surface of peripheral blood cells from patients with AMD, was shown to cause PI3K/Akt/GSK3 insensitivity, high GSK3 activity associated with insulin resistance, and type 2 DM." (PMID 36289698, 2022).
ocular infection (2 papers, 2020 to 2023). "Upon ocular infection of IL-17RA-/- and IL-17RC-/- mice with HSV-IL-2, demyelination was detected in all samples of both IL-17RA-/- and IL-17RC-/- infected mice." (PMID 36817487, 2023). "Trigeminal ganglia (TG) from some WT and IL17A−/−, IL17RA−/−, IL17RC−/−, and IL17RA−/−RC−/− mice that survived ocular infection were isolated on day 28 PI." (PMID 32516406, 2020).
ocular sarcoidosis (2 papers, 2014). A leading cause of inflammatory eye disease is sarcoidosis. "Overexpression of IL17RC also associates with inflammation, such as ocular sarcoidosis." (PMID 25089247, 2014). "In this study, we found that the frequency of IL-17RC+CD8+ cells was increased in ocular sarcoidosis patients, which strongly suggests involvement of inflammatory CD8+ T cells in sarcoidosis." (PMID 24885153, 2014). "An elevated expression of IL-17RC on CD8+ T cells in peripheral blood was found in patients with ocular sarcoidosis as compared to healthy controls." (PMID 24885153, 2014). "Our results suggested a potential involvement of IL-17RC+CD8+ T cells in pathogenesis of ocular sarcoidosis." (PMID 24885153, 2014). "Immunohistochemistry assays demonstrated that IL-17RC expression in the retinal tissues of patients with clinically active ocular sarcoidosis was higher than its expression in the eye from patients with quiet disease clinically but small focal inflammation histopathologically." (PMID 24885153, 2014). "Therefore, we first tested whether the expression of IL-17RC was increased on PBMCs from patients with ocular sarcoidosis." (PMID 24885153, 2014). "Importantly, we found that IL-17RC expression was significantly elevated only in CD8+ T cells in sarcoidosis patients as compared to healthy controls, suggesting a potential role the IL-17RC+CD8+ T cells may play in the pathogenesis of ocular sarcoidosis." (PMID 24885153, 2014). "Previous studies have suggested that IL-17RC+ cells may be able to migrate to the eye, we therefore tested whether IL-17RC+ cells could be found in the retinal tissues of patients with either active or quiet ocular sarcoidosis." (PMID 24885153, 2014). "Therefore, in this study, we explored whether the expression of IL-17RC was changed in ocular sarcoidosis patients." (PMID 24885153, 2014). "Therefore, the elevated expression of IL-17RC in the peripheral blood of patients with ocular sarcoidosis may be due to the effect of increased serum level of IL-17 in these patients." (PMID 24885153, 2014). "Interestingly, we found a significant increase in the serum level of IL-17 in patients with ocular sarcoidosis as compared to healthy controls, which may be responsible for the induction of IL-17RC on CD8+ cells." (PMID 24885153, 2014). "Our results demonstrated an elevated expression of IL-17RC on CD8+ T cells in patients with sarcoidosis, supporting a potential role of these T cells played in the pathogenesis of ocular sarcoidosis." (PMID 24885153, 2014). "Intriguingly, the frequency of IL-17RC+ cells among CD3+CD4+ helper T cells, CD14+ monocytes, CD19+ B cells, and CD56+ NK cells was similar between healthy controls and ocular sarcoidosis patients." (PMID 24885153, 2014). "A low frequency of IL-17RC+ cells in the whole blood was found on CD8+ T cells, not only in healthy controls but also in patients with ocular sarcoidosis." (PMID 24885153, 2014).
prostate tumor (2 papers, 2020 to 2025). "In Pten conditional knockout mouse models of PCa, compared to IL-17RC knockout and lean controls, both IL-17RC wild-type and obese mice demonstrated substantial co-upregulation of PD-1 and PD-L1 in prostate tumor tissues." (PMID 41488631, 2025).
scoliosis (2 papers, 2012 to 2025). A congenital or acquired spinal deformity characterized by lateral curvature of the spine. "Tryptophan hydroxylase (TPH1 rs10488682), insulin-like growth factor (IGF1 rs5742612), neurotrophin 3 (NTF3 gene promoter at rs11063714), interleukin-17 receptor C (IL17RC rs708567), melatonin receptor 1B (MTNR1B rs4753426) were identified as risk factors for scoliosis curve progression." (PMID 39781499, 2025).
ankylosing spondylitis (1 paper, 2021). An autoimmune chronic inflammatory disorder characterized by inflammation in the vertebral joints of the spine and sacroiliac joints. "This study is aimed at investigating IL-17A, IL-17F, IL-17RA, and IL-17RC polymorphisms as potential biomarkers of disease susceptibility, clinical parameters, and anti-TNF treatment outcome in a cohort of Polish ankylosing spondylitis patients." (PMID 34744511, 2021).
Arthritis (1 paper, 2014). Inflammation of a joint. "The objective was to determine the variability in expression of IL-17A, IL-17F and their receptors IL-17RA and IL-17RC in the synovia of patients with arthritis." (PMID 25146432, 2014).
autism (1 paper, 2022). Persistent deficits in social interaction and communication and interaction as well as a markedly restricted repertoire of activity and interest as well as repetitive patterns of behavior. "Interestingly, neutrophils of individuals with autism were found to express the IL-17RC subunit, which was absent in the neutrophils of control subjects." (PMID 36268027, 2022).
colitis (1 paper, 2025). Inflammation of the colon. "After DSS treatment, IL-17RC KO in Tak1ΔM/ΔM mice completely converted the resistant phenotype to the sensitive phenotype, suggesting that IL-17RC receptor is required for IL-17A–mediated inhibition of chemokine expression and resistance to DSS-induced colitis." (PMID 40749055, 2025).
coronary atherosclerosis (1 paper, 2025). Atherosclerosis of the coronary vasculature. "IL17RC shows a significant negative association with CAD (OR = 0.96, p = 2.50E-08) and a stronger significant negative association with coronary atherosclerosis (OR = 0.88, p = 6.00E-09)." (PMID 40276600, 2025).
cutaneous candidiasis (1 paper, 2015). Candidiasis of the skin manifested as eczema-like lesions of the interdigital spaces, perleche, or chronic paronychia. "The similarities between WT littermate controls and IL-17RE-/- mice indicate that IL-17C signaling via IL-17RE is not essential for protection from or the resolution of cutaneous candidiasis, whereas IL-17A signaling through IL-17RA/IL-17RC is nonredundant." (PMID 25849644, 2015).
depression (1 paper, 2022). "Since it is unclear whether CUMS aggravates neuroinflammation through the imbalance between Th17 and Treg, the present study further evaluated the mRNA and protein expression of IL-17A and its receptor IL-17Rc in a model of depression." (PMID 36430328, 2022). "Excessive IL-17A combines with the specific receptor IL-17Rc in microglia and astrocytes, further activates microglia M1 phenotype and astrocyte A1 phenotype and triggers IDO enzyme activity, thereby causing neurotransmitter metabolism and inducing depression-like behaviors." (PMID 36430328, 2022).
idiopathic scoliosis (1 paper, 2018). A scoliosis with no known cause. "It was reported that the IL-17RC*G/G genotype was significantly associated to the curve severity of adolescent idiopathic scoliosis." (PMID 29584788, 2018).
intestinal cancer (1 paper, 2022). "This was also associated with reducing IL-1β, Cox-2, and IL-17RC expression suggesting proinflammatory and protumorgenic roles of IL-17F in intestinal cancer." (PMID 35012470, 2022).
liver fibrosis (1 paper, 2018). "In the present study, we evaluated the capacity of the BM-MSCs in the modulation of cytokines milieu and signal transducers, based on unique inflammatory genes Il17a and Il17f and their receptors Il17rc and their effect on the IL6/STAT3 pathway in CCl4-induced liver fibrosis in rats." (PMID 30346985, 2018).
lymphangioma (1 paper, 2008). A benign lesion composed of dilated lymphatic channels. "IL-17RC expression in 51 normal human tissues and two benign tumors (i.e., lymphangioma and parathyroid adenoma) on the tissue microarrays was determined by immunohistochemical staining, using two polyclonal antibodies against IL-17RC." (PMID 18928529, 2008).
multiple sclerosis (1 paper, 2011). A progressive autoimmune disorder affecting the central nervous system resulting in demyelination. "Further studies are needed to better understand the roles of these receptors in multiple sclerosis and its treatment and to clarify the utility of GPR3 and IL17RC expression levels in the blood as markers of long-term prognosis." (PMID 22216338, 2011).
nephritis (1 paper, 2018). Inflammation of renal tissue. "However, although Il17rc−/− and Il17ra−/− mice developed hyper Th17 cells with elevated Il22 expression and skin inflammation, they did not develop SLE-nephritis and Sjögren’s-like disease." (PMID 30013031, 2018).
osteoporosis (1 paper, 2013). A condition of reduced bone mass, with decreased cortical thickness and a decrease in the number and size of the trabeculae of cancellous bone (but normal chemical composition), resulting in increased fracture incidence. "By the comparison of gene chips from five osteoporosis patients and four normal samples of bone marrow stem cell, we identified genes (IL17RC, COL1A1, and ESR1) that directly interact with the OPG gene." (PMID 23731710, 2013). "The expressions of IL17RC, COL1A1, and ESR1 in bone marrow mesenchymal cell are expected to be used in developing biomarkers for detecting osteoporosis and for screening osteoporosis risk groups." (PMID 23731710, 2013). "The expression pattern of IL17RC, COL1A1, and ESR1 can be useful in osteoporosis detection, which may help in identifying those populations at high risk for osteoporosis, and in directing treatment of osteoporosis." (PMID 23731710, 2013).
pancreatic cancer (1 paper, 2024). "Regulate cluster cell development and stem cell characteristics of pancreatic cancer cells by increasing the expression of DCLK1, POU2F3, ALDH1A1, and IL17RC." (PMID 39906741, 2024). "IL-17 could also regulate cluster cell development and stem cell characteristics of pancreatic cancer cells by increasing the expression of DCLK1, POU2F3, ALDH1A1, and IL17RC." (PMID 39906741, 2024).
papilloma (1 paper, 2022). A benign epithelial neoplasm that projects above the surrounding epithelial surface and consists of villous or arborescent outgrowths of fibrovascular stroma. "In the skin papilloma model, Il17ra(T779A)-KI significantly decreased tumor burden compared to the WT, while Il17rc-KO abolished papilloma development." (PMID 36009523, 2022).
periodontal disease (1 paper, 2024). "Our analysis revealed a co-expression network comprising 216 genes, including prominent hub genes such as IL17RC, CCN2, BMP7, TPM1, and TIMP1, which are implicated in periodontal disease." (PMID 39659491, 2024). "Among the top five hub genes highlighted in this interactome are IL17RC, CCN2, BMP7, TPM1, and TIMP1, all of which have been implicated in periodontal disease in conjunction with peri-implant disease." (PMID 39659491, 2024). "The study identified 216 genes, with top hub genes like IL17RC, CCN2, BMP7, TPM1, and TIMP1 involved in periodontal disease." (PMID 39659491, 2024).
pneumonia (1 paper, 2019). An acute, acute and chronic, or chronic inflammation focally or diffusely affecting the lung parenchyma, caused by an infection in one or both of the lungs (by bacteria, viruses, fungi, or mycoplasma.). "Although the significance of IL-17RC in HAdV-55-induced pneumonia is unidentified, recent studies indicated that the lung epithelium express IL-17RC which promotes respiratory allergy or pulmonary defense against Klebsiella pneumoniae." (PMID 30787914, 2019). "The up-regulation of IL-17RC on the lung epithelium might enhance the inflammatory response in the lung after HAdV-55 invasion, and therefore reflects the extent of pneumonia." (PMID 30787914, 2019).
prostate adenocarcinoma (1 paper, 2020). "Moreover, IL-17RC(+) mice developed an increased number of invasive prostate adenocarcinomas with higher rates of cellular proliferation and lower apoptosis than IL-17RC(-) mice." (PMID 32537467, 2020).
Pruritus (1 paper, 2022). Pruritus is an itch or a sensation that makes a person want to scratch. "We identified several pruritus-associated genes increased by IDL, IDC and IDL + IDC (e.g., BRCA2, KRT5, TCF4), as well as several such genes decreased by IDL, IDC and/or IDL + IDC (e.g., IL2RG, TRPV3, TNFSF15, IL17RC)." (PMID 36430783, 2022).
pulmonary fibrosis (1 paper, 2026). Chronic progressive interstitial lung disorder characterized by the replacement of the lung tissue by connective tissue, leading to progressive dyspnea, respiratory failure, or right heart failure. "In this study, a Bleomycin (BLM)-induced murine model of pulmonary fibrosis was used to study the effect of neutralization of IL-17RA and IL-17RC on ECM remodeling, MMPs, and the fibrinolytic system." (PMID 42298666, 2026).